CTLA4 (cytotoxic T-lymphocyte associated protein 4)
Diseases named in the same sentence as CTLA4 in open-access papers (continued):
Sharing a sentence is not in itself a finding about the gene and the disease.
prostate carcinoma (150 papers, 2010 to 2025). A carcinoma that arises from epithelial cells of the prostate gland. "Phenocopying CHD1 depletion, pharmacological inhibition of IL-6 and dual blockade of PD-1/CTLA-4 showed synergistic effects in preclinical models of PTEN-deficient prostate cancer." (PMID 36776288, 2023). "In immunotherapy for prostate cancer, cytotoxic T lymphocyte-associated antigen 4 (CTLA4), programmed death ligand-1 (PD-L1), and programmed death-1 (PD-1) inhibitors have shown promising outcomes in terms of anti-tumor immune therapy." (PMID 37388224, 2023). "Immune checkpoint inhibitors that target cytotoxic T-lymphocyte-associated protein 4 (CTLA-4), programmed death 1 (PD-1), and its ligand (PD-L1) display minimal or no activity as single agents or in combination with AR inhibitors in advanced prostate cancers." (PMID 36776288, 2023). "The main therapeutic targets of ICT in prostate cancer are the cytotoxic T lymphocyte-associated antigen 4 (CTLA-4), programmed cell death protein 1 (PD-1) and its ligand (PD-L1)." (PMID 36925917, 2023). "The immune checkpoint molecules, such as programmed cell death 1 (PD-1), PD-1 ligand 1 (PD-L1) and cytotoxic T-lymphocyte associated antigen 4 (CTLA-4), have demonstrated a remarkable, durable response in bladder cancer, prostate cancer and kidney cancer." (PMID 35143414, 2022). "This was associated with limited efficacy of anti-CTLA-4 monotherapy except in a small subset of patients with prostate cancer." (PMID 33820953, 2021). "LINC00861 was found to be potentially intervening targets of immunotherapy for prostate cancer patients, which was significantly associated with PD-1 and CTLA4." (PMID 33665192, 2021). "Increased Treg infiltration in the tumour microenvironment through C-C chemokine receptor 4 (CCR4) with the high expression level of the cytotoxic T-lymphocyte-associated protein 4 (CTLA-4) and PD-1 markers was linked with a poor prognosis in prostate cancer." (PMID 33924671, 2021). "The majority of prostate cancer patients were identified with immunological ignorance (89.8%), upregulated cytotoxic T lymphocyte-associated protein 4 (CTLA4) (58.8%), and upregulated decoy receptor 3 (DcR3) (51.6%)." (PMID 32552802, 2020). "Here, we present a case of a complete metabolic and serologic remission in a patient with dMMR/MSI-H mCRC and Lynch syndrome-associated prostate cancer under treatment with combined anti-PD-1 and anti-CTLA-4 blockade with nivolumab and ipilimumab after progression under pembrolizumab monotherapy." (PMID 37569431, 2023). "Interestingly, higher pre-treatment levels of intracellular CTLA-4 has been associated with a better overall survival in prostate cancer patients treated with Ipilimumab." (PMID 28423678, 2017). "However, in another report, a prostate cancer patient who experienced a sustained complete response to CTLA-4 blockade mounted a strong humoral response against a small number of proteins, including one that is mutated in 5.5 % of prostate cancers." (PMID 26788324, 2016). "In anti-CTLA-4 monotherapy, the incidences of both all-grade and severe diarrhea occurred most frequently in prostate cancer patients (41.9 %, 95 % CI 37.9%–47.9; 14.8 %, 95 % CI 11.5%–18.7 %, respectively)." (PMID 39866435, 2025). "In prostate cancer, CTLA-4 is a critical immune checkpoint receptor that contributes to immune evasion by suppressing T-cell activation." (PMID 41228234, 2025). "Immune checkpoints, such as PD-1/PD-L1 and CTLA-4, play a pivotal role in modulating the immune response, allowing prostate cancer cells to evade immune surveillance." (PMID 40535811, 2025). "Clonality was assessed in the context of immune-related adverse events (irAEs) after anti-CTLA-4 treatment of prostate cancer patients, showing that the expansion more than 55 CD8+ T-cell clones in the peripheral blood preceded the development of severe irAEs." (PMID 38903504, 2024).
prostate carcinoma (continued). "The refractory response to PD-1/PD-L1 and CTLA4 blockade by immunologically “cold” tumors like CNS, pancreatic, or prostate cancer gave urgency to finding alternatives to these targets that are mainly dependent on an active immune response." (PMID 36825029, 2023). "In a mouse model of prostate cancer, cryoablation combined with anti-CTLA-4 antibody treatment prolonged the survival time of the mice by 14.8 days." (PMID 36761748, 2023). "Despite initial challenges, several ongoing clinical trials are investigating the use of CTLA-4 or PD-1/PD-L1 inhibitors in castration-sensitive prostate cancer and low disease burden when the host is presumed to have a stronger immune system (NCT03007732)." (PMID 37762648, 2023). "Ipilimumab, a popular inhibitor of the immune checkpoint molecule CTLA-4, was used to treat in prostate cancer patients after it was approved by the FDA to treat melanoma." (PMID 35892678, 2022). "Combined application of vaccine that contains RM-1 cells which expressed 4-1BBL with CTLA-4 blockade can induce the regression of prostate cancer cells, showing the treatment potency of 4-1BBL in cancer immunotherapy." (PMID 35585975, 2022). "Among monoclonal antibodies, PD-1 inhibitors, PD-L1 inhibitors, and CTLA-4 inhibitors have the potential to become the drugs of the future for patients with prostate cancer." (PMID 35411277, 2022). "Recent studies of patients from large-scale clinical trials have demonstrated that elevated IL-8 correlates with a poorer prognosis across cancer types as well as in prostate cancer specifically, for both anti-CTLA-4 and anti-PD-1/PD-L1 CPI therapies." (PMID 33820953, 2021). "We investigated the effect of combining anti-CTLA-4 treatment with the STAT3 inhibitor GPB730 on tumor growth in a prostate cancer mouse tumor model." (PMID 33786638, 2021). "GPB730 enhanced the CD45 + immune cell infiltration in the prostate cancer mouse tumors of anti-CTLA-4-treated mice which was confirmed by IHC staining of CD45-positive cells in RM-1 tumors." (PMID 33786638, 2021). "In conclusion, STAT3 inhibition by GPB730 enhances the antitumoral activity of anti-CTLA-4 in a prostate cancer mouse model, possibly by blocking STAT3 mediated resistance mechanisms such as Tregs in the immunosuppressive environment." (PMID 33786638, 2021). "While others have shown PD-L1 expression on the surface of CTCs in other solid tumors including prostate cancer, we have detected 4 different checkpoint ligands PD-L1, PD-L2, B7-H3, and CTLA-4 on CTCs." (PMID 33602330, 2021). "Ipilimumab is an anti-CTLA4 approved for the treatment of several tumors, and tested in metastatic castration-resistant prostate cancer." (PMID 35008298, 2021). "CTLA-4 blockade by ipilimumab has shown some efficacy in prostate cancer, however with only a subset of patients reaching long-term remission and increased survival." (PMID 33786638, 2021). "Blocking TGF-β and CTLA-4 simultaneously in mouse models of castration-resistant prostate cancer with bone metastasis significantly inhibited the progression of bone metastasis and improved the overall survival rate compared with CTLA-4 inhibitor monotherapy." (PMID 34877360, 2021). "In the present study, we investigated the possibility of enhancing the efficacy of anti-CTLA-4 therapy in a syngeneic prostate cancer mouse model by combining treatment with the STAT3 inhibitor GPB730." (PMID 33786638, 2021). "With continued identification of targetable immune checkpoints and development of CPIs, such as an anti-CTLA-4 antibody, further clinical trials were conducted that evaluated them in the setting of prostate cancer." (PMID 33820953, 2021). "We here demonstrate that the STAT3 inhibitor GPB730 enhances the antitumoral effect of anti-CTLA-4 treatment in a syngeneic prostate cancer mouse model." (PMID 33786638, 2021).
prostate carcinoma (continued). "B7-H3 and CTLA-4 were selected as the other checkpoints to characterize in this study for their prevalence on prostate cancer cells and importance in the tumor-immune interactions, respectively." (PMID 33602330, 2021). "In conclusion, STAT3 inhibition by GPB730 enhances the antitumoral activity of anti-CTLA-4 and decreases the intratumoral Treg frequency in a prostate cancer mouse model." (PMID 33786638, 2021). "In the present study, we sought to investigate to enhance the efficacy of anti-CTLA-4 therapy against prostate cancer by the combination with STAT3 inhibition." (PMID 33786638, 2021). "Nevertheless, different immunotherapy-based strategies have been tested in prostate cancer patients, including vaccine-based therapies and CTLA-4 and PD1-PDL1 inhibition." (PMID 35008298, 2021). "Since upregulated programmed cell death 1 (PD-1) and/or CTLA4 often co-occur with other IEMs, these results provide a plausible explanation for the failure of immune checkpoint inhibitor monotherapy for prostate cancer." (PMID 32552802, 2020). "Low expression of the miR-424-3p was a significant predictor for prostate cancer aggressiveness and outcome, and this was in close correlation with CTLA-4 expression." (PMID 32316552, 2020). "This inspired a clinical trial combining CTLA-4 blockade and PD-1 inhibition for advanced prostate cancer." (PMID 32630247, 2020). "The GVAX cellular vaccine was evaluated alone and in combination with anti-CTLA-4 blocking antibodies in the TRAMP murine model of prostate cancer, and it demonstrated antitumor activity only with the combination treatment." (PMID 33008010, 2020). "Prostate cancer patients with upregulated CTLA4 or PD-1 expression also exhibited other immune evasion mechanisms that obstruct the cancer immunity cycle." (PMID 32552802, 2020). "Upregulated PD-1 expression (27.8%) was accompanied by upregulated CTLA4 expression in prostate cancer patients." (PMID 32552802, 2020). "Clinical trials for anti-CTLA-4 and anti-PD-1 combinational therapy have demonstrated promising anti-tumor activity in lung cancers, mesothelioma, esophagogastric cancer, prostate cancer, and sarcoma." (PMID 32111080, 2020). "Another preclinical study showed that whole-tumor vaccines producing granulocyte macrophage colony-stimulating factor (GM-CSF) greatly enhanced anti-CTLA-4 blockade efficacy against pancreatic and prostate cancers." (PMID 30191140, 2018). "As some of these factors can be specifically manipulated, and anti-CTLA4 therapies are already used to treat advanced prostate cancer patients future functional studies will be performed." (PMID 28472073, 2017). "It has also been previously reported that while prostate cancer patients had a similar frequency of total Tregs in peripheral blood as healthy donors, the CTLA-4+ Tregs from patients had greater suppressive functionality." (PMID 28936253, 2016). "For advanced prostate cancer, it was shown that patients who clinically responded to CTLA-4 blockade also developed an enhanced antibody response to a greater number of endogenous antigens than non-responders." (PMID 26788324, 2016). "It was also shown that a prostate cancer patient with a sustained complete response to CTLA-4 blockade mounted a strong humoral response against a small number of proteins." (PMID 26788323, 2016). "Further supporting a role of inflammation-induced immune-suppression in the development of early-onset prostate cancer, we observed significant up-regulation of CTLA4 and IDO1/TDO2 pathways in tumors of the young cohort." (PMID 28027300, 2016). "Evidence from bladder and prostate cancer patients also suggests that anti-CTLA-4 treatment leads to an increased intra-tumoral Teff/Treg ratio." (PMID 25859247, 2015). "The U.S. Food and Drug Administration (FDA) approval of the checkpoint inhibitor anti-CTLA4 and the Provenge prostate cancer vaccine has been followed by recent FDA approvals of anti-PD-L1/PD-1 immune checkpoint inhibitors." (PMID 26374823, 2015).
prostate carcinoma (continued). "Previous studies in murine prostate cancer models have demonstrated that CTLA-4 blockade promotes anti-tumor activity and works synergistically with GM-CSF-expressing tumor vaccines." (PMID 23557194, 2013). "We examined the anti-tumor effects of combination therapy with GVAX and anti-CTLA-4 in an autochthonous prostate cancer model expressing HA in a prostate-restricted manner." (PMID 23557194, 2013). "Ipilimumab, an anti-CTLA-4 antibody, was tested in order to potentiate endogenous antitumor immunity to prostate cancer through combination immunotherapy with CTLA-4 blockade and GM-CSF." (PMID 22530130, 2012). "In the present work, we investigated the effect of a vaccine combined with 4-1BBL-expressing tumor vaccine and CTLA-4 blockade on the survival of C57BL/6 mice transplanted subcutaneously with prostate cancer RM-1 cells." (PMID 22312406, 2012). "In this study, we examined the effectiveness of 4-1BBL-expressing tumor cell vaccine in combination with CTLA-4 blockade on rejection of murine prostate cancer RM-1." (PMID 22312406, 2012). "Moreover, MIT@ZIF-8 treatment increases the abundance of cytotoxic CD8+ T cells and reduces the amount of immunosuppressive regulatory T cells in tumors, thereby enhancing anti-tumor immunity and sensitizing prostate cancer to anti-CTLA-4 immunotherapy." (PMID 39950857, 2025). "Ipilimumab is a human monoclonal antibody against the CTLA-4 antigen, and several studies have reported significant effects of combination of radiotherapy and Ipilimumab in the treatment of metastatic melanoma, non-small cell lung cancer and prostate cancer." (PMID 38259489, 2023). "While we observed this effect may be driven by IL-6 blockade, previous studies in prostate cancer observed elevated numbers of IFN-γ–producing CD4+ T cells upon administration of CTLA-4–blocking Abs." (PMID 36881480, 2023). "In the setting of prostate cancer, upregulation of either PD-L1 or CTLA-4 may be indicative of a more aggressive disease course and an unfavorable prognosis." (PMID 37762648, 2023). "However, upregulation of VISTA on infiltrating immune cells has been reported in prostate cancer treated with ipilimumab (anti-CTLA-4), suggesting its role in anti-CTLA-4 resistance." (PMID 36845142, 2023). "Nonetheless, long-term survival benefits and sustained complete responses have been reported in some mCRPC patients receiving a CTLA-4 inhibitor (Ipilimumab), suggesting that selected prostate cancer patients may benefit from a checkpoint blockade." (PMID 35892678, 2022). "LINC00861 was identified as a potential immunotherapy intervention target in patients with prostate cancer and was significantly correlated with CTLA4, which is consistent with the findings of our correlation study between prognosis-related lncRNAs and immunological checkpoints." (PMID 36105091, 2022). "Blocking the PD-1/PD-L1 immune checkpoint while blocking the CTLA-4 immune checkpoint may represent a novel, potential immunotherapy for prostate cancer." (PMID 35706452, 2022). "The expression level of PD-1 on Tregs, similarly to the expression of CTLA4 showed a mild but progressive increase in brachytherapy-treated prostate cancer patients, reaching significantly increased levels 36 months after seed implantation compared to patients before therapy." (PMID 35804830, 2022). "Furthermore, the levels of circulating and intratumoral Tregs have been observed to be increased by anti-CTLA-4 treatment in patients with prostate cancer." (PMID 33786638, 2021). "However, prostate cancer tumors benefit directly and indirectly through CTLA-4-mediated immunosuppression and a general anergic state." (PMID 33820953, 2021). "Also, a tumor microenvironment skewed in favor of a CD4 + T helper 1 (Th1) effector T cell infiltration is conditional for the response of castration resistant prostate cancer metastasis to anti-CTLA-4." (PMID 33602280, 2021).
prostate carcinoma (continued). "Here the authors show that IRE, followed by anti-CTLA-4 blockade, elicits the expansion of tumor antigen-specific CD8+ T cells and is associated with tissue residency and improved anti-tumor immune response in a preclinical model of prostate cancer." (PMID 34162858, 2021). "Of note, in prostate cancer, LINC00861 was closely associated with T cells regulatory, macrophages M2 and mast cells resting as well as a series of immune checkpoints, including PD1, PD-L1, and CTLA4." (PMID 33665192, 2021). "CTLA-4 is a prominent immune checkpoint present in prostate cancer." (PMID 33820953, 2021). "Finally, VISTA and PD-1 pathways were increased following CTLA-4 blockade in patients suffering from prostate cancer indicating that the manipulation of VISTA also acts in synergy and non-redundant to CTLA-4 blockade." (PMID 32674488, 2020). "PD-L1 and VISTA expression on these immune cell subsets may contribute to the poor responsiveness of prostate cancer patients to anti-CTLA-4 therapy." (PMID 32194568, 2020). "In another phase I trial for prostate cancer, a vaccine containing two irradiated prostate cancer cell lines that express GM-CSF (GVAX-PCa) again in combination with targeting the immune suppressive immune checkpoint molecule CTLA-4 by ipilimumab, induced an increased expression of CD40 by DCs." (PMID 31555582, 2019). "The expression of the inhibitory immune checkpoints PD-L1 and VISTA may explain the poor responsiveness of prostate cancer patients to CTLA-4 blockade and supports the design of a combination therapy targeting both molecules." (PMID 29494517, 2018). "Thus, a significantly higher expression of PD-L1 and VISTA on T cells, CD8+ T cells, and CD68+ macrophages in tumor tissues from prostate cancer patients after anti-CTLA-4 therapy was reported." (PMID 29494517, 2018). "Additional sample sizes are required to confirm whether over-expression of IDO1 and/or CTLA4 in tumors may be predictive of prostate cancer recurrence in young men." (PMID 28027300, 2016). "Indeed, recent evidence suggests that increased overall survival of prostate cancer patients treated with Ipilimumab and the vaccine GVAX was associated with increased with pre-treatment levels of CTLA-4+ and PD-1+ T cells in circulation." (PMID 25428917, 2015). "Similarly, development of a prostate-specific membrane antigen (PSMA)-specific antibody response was associated with improvement in overall survival after treatment with prostate cancer GVAX combined with ipilimumab (anti-CTLA-4)." (PMID 26143264, 2015). "In addition, the CTLA-4 blocking antibody ipilimumab has shown clinical activity in a variety of cancer types, including prostate cancer." (PMID 26196012, 2014). "These experiments corroborate recent clinical data, which suggest that the combination of CTLA-4 blockade and cell-based, GM-CSF-secreting vaccines may have significant anti-tumor effects in men with prostate cancer." (PMID 23557194, 2013). "To determine whether expression of the immune checkpoint molecule CTLA-4 could potentially be restraining the vaccine response of prostate/prostate cancer specific cells, we stained the prostate-specific CD8 T cells for CTLA-4 expression." (PMID 23557194, 2013). "Collectively, these preclinical experiments suggest that appropriate manipulation of T cell costimulatory and inhibitory signals may provide a basis for CTLA-4 based prostate cancer immunotherapy." (PMID 24216992, 2013). "In summary, we concluded that the combination of activation of 4-1BB and blockade of CTLA-4 has a higher potential antitumor effect and may offer a new strategy for prostate cancer immunotherapy." (PMID 22312406, 2012). "An SV40 TAg transgenic model of prostate cancer has been used to study the effects of combining blockade of cytotoxic T lymphocyte antigen 4 (CTLA-4) and vaccination with granulocyte macrophage colony stimulating factor (GM-CSF;Gvax) and subsequent derivatives of this vaccine strategy." (PMID 20958993, 2010).